ADGRG1 (adhesion G protein-coupled receptor G1)
Description:
Adhesion G protein-coupled receptor (aGPCR) for steroid hormone 17alpha-hydroxypregnenolone (17-OH), which is involved in cell adhesion and cell-cell interactions. Ligand binding causes a conformation change that triggers signaling via guanine nucleotide-binding proteins (G proteins) and modulates the activity of downstream effectors, such as RhoA pathway. ADGRG1 is coupled to G(12) and/or G(13) G proteins (GNA12 and GNA13, respectively) and mediates the activation Rho small GTPases. Acts as a potent suppressor of ferroptosis: binding to 17-OH-binding initiates signaling that down-regulates CD36 and alleviates ferroptosis-induced liver injury (By similarity). Ligand-binding also induces cell adhesion activity via association with proteins such as collagen III/COL3A1 and TGM2 (By similarity). Mediates cell matrix adhesion in developing neurons and hematopoietic stem cells (By similarity). Involved in cortical development, specifically in maintenance of the pial basement membrane integrity and in cortical lamination: association with COL3A1 in the developing brain inhibits neuronal migration via activation of the RhoA pathway. Together with TGM2, acts as a regulator of myelination and myelin repair in oligodendrocyte precursor cells (By similarity). Acts as a hemostatic sensor of shear force: G protein-coupled receptor signaling is activated in response to shear force in platelets, promoting G(13) G protein signaling, and platelet shape change and aggregation in a COL3A1-dependent manner. Acts as an inhibitor of VEGFA production thereby inhibiting angiogenesis through a signaling pathway mediated by PRKCA. Plays a role in the maintenance of hematopoietic stem cells in bone marrow niche (By similarity). Plays an essential role in testis development (By similarity). [Isoform 5]: Adhesion G protein-coupled receptor (aGPCR) for phosphatidylserine, which is involved in microglia-mediated synapse pruning during development (By similarity). Required to maintain appropriate synaptic numbers in several brain regions in a time- and circuit-dependent fashion: phosphatidylserine-binding acts as a 'eat-me' signal for apoptotic cells, leading to microglial engulfment of phosphatidylserine-positive synapses (By similarity).
Synonyms: GPR56; TM7LN4; TM7XN1; BFPP; BPPR; CDCBM14B; CDCBM15A
Tractability: Antibody: UniProt places it where antibodies can reach, with high confidence; its Gene Ontology location is reachable by antibodies, with high confidence; UniProt predicts a signal peptide or a membrane-spanning region. PROTAC: UniProt records ubiquitination sites on it; ubiquitination databases record sites on it.
Target class: Family B G protein-coupled receptor; Membrane receptor
Gene: Protein-coding gene on chromosome 16 (57,610,652 to 57,665,580, forward strand). Ensembl gene ENSG00000205336.
Subcellular location: Cell membrane; Secreted (Adhesion G protein-coupled receptor G1, N- terminal fragment); Membrane raft (Adhesion G protein-coupled receptor G1, C- terminal fragment)
Gene Ontology:
Molecular function: G protein-coupled receptor activity; heparin binding; protein binding; collagen binding; extracellular matrix binding; transmembrane signaling receptor activity
Biological process: angiogenesis; brain development; cell adhesion; cell migration; negative regulation of cell population proliferation; phospholipase C-activating G protein-coupled receptor signaling pathway; positive regulation of cell adhesion; positive regulation of vascular endothelial growth factor signaling pathway; regulation of platelet aggregation; Rho protein signal transduction; Rho-activating G protein-coupled receptor signaling pathway; cell-cell signaling; cerebral cortex radial glia-guided migration; G protein-coupled receptor signaling pathway; layer formation in cerebral cortex; negative regulation of ferroptosis; negative regulation of neuron migration; positive regulation of Rho protein signal transduction; anatomical structure formation involved in morphogenesis; cell surface receptor signaling pathway; positive regulation of signal transduction; regulation of cell population proliferation; seminiferous tubule development; tube development
Cellular component: extracellular exosome; extracellular region; membrane raft; plasma membrane; glial limiting end-foot; membrane
Genetic constraint (gnomAD): Loss-of-function variants: 50 observed, 72.64 expected, observed/expected ratio (o/e) 0.69, 90% interval 0.55 to 0.87. The upper end of that interval is the gene's LOEUF score, 0.87, which puts it in group 3 of 6, group 1 being the genes least tolerant of losing a copy. Missense variants: 777 observed, 891.57 expected, observed/expected ratio (o/e) 0.87, 90% interval 0.82 to 0.93. Synonymous variants: 389 observed, 390.32 expected, observed/expected ratio (o/e) 1, 90% interval 0.92 to 1.08.
Gene-disease validity (ClinGen):
ClinGen rates the evidence that ADGRG1 causes each of these diseases.
bilateral frontoparietal polymicrogyria (autosomal recessive): Definitive. A descriptive term reflecting increased gyral folding in the frontoparietal regions as determined by magnetic resonance imaging.
Homologues: Orthologues: chimpanzee ADGRG1 (99% identical), macaque ADGRG1 (94% identical), dog ADGRG1 (85% identical), pig ADGRG1 (85% identical), rabbit ADGRG1 (80% identical), rat Adgrg1 (80% identical), mouse Adgrg1 (79% identical), guinea pig ADGRG1 (66% identical), tropical clawed frog adgrg1 (29% identical). Paralogues in human: ADGRG3 (25% identical), ADGRG5 (24% identical), ADGRG2 (22% identical), ADGRG6 (21% identical), ADGRG4 (21% identical), ADGRL3 (19% identical), ADGRL1 (18% identical), ADGRL2 (18% identical), ADGRE2 (18% identical), ADGRE3 (17% identical), ADGRD2 (17% identical), ADGRE1 (17% identical), and 30 more.
Diseases named in the same sentence as ADGRG1 in open-access papers:
ADGRG1 is named in the same sentence as 117 diseases in open-access papers, as found by Europe PMC text mining. Sharing a sentence is not in itself a finding about the gene and the disease. The quoted sentences say what the papers report.
melanoma (26 papers, 2012 to 2025). A malignant, usually aggressive tumor composed of atypical, neoplastic melanocytes. "ADGRG1 even plays opposite roles in different tumors; for example, it serves as a suppressor in melanoma but possesses oncogenic property in glioblastoma, ovarian cancer, colon cancer, pancreatic cancer, non-small-cell lung cancer, and esophageal cancer." (PMID 34367958, 2021). "ADGRG1 knockdown resulted in melanoma growth inhibition and regression, while knockdown of the other 2 aGPCRs reduced lung (ADGRF5) and/or bone metastasis (ADGRE5, ADGRF5)." (PMID 29468160, 2018). "We previously reported that the adhesion G-protein-coupled receptor GPR56/ADGRG1 is downregulated in melanoma metastases." (PMID 29450192, 2018). "We first focused our attention on TG2 because it is a known binding partner of ADGRG1 in melanoma cells." (PMID 29809138, 2018). "The aGPCR GPR56/ADGRG1 regulates central nervous system myelination and melanoma progression by interacting with its ligand, tissue transglutaminase 2 (TG2), but the molecular basis for this interaction is largely undefined." (PMID 33037308, 2020). "For instance, in skin cutaneous melanoma (SKCM), ADGRG1/GPR56, GPR143, and EDNRB are highly overexpressed and highly expressed in magnitude compared to normal skin in >90% of melanoma samples." (PMID 31765370, 2019). "However, it is of interest that a key regulator of myelination, Adgrg1, has also been recently shown to reduce fibronectin deposition and inhibit cell-ECM signalling to prevent metastatic melanoma growth." (PMID 31180326, 2019).
polymicrogyria (22 papers, 2013 to 2025). A developmental brain abnormality characterized by an excessive amount of small convolutions on the surface of the brain and cognitive dysfunction. "We identified a known disease-linked mutation in the polymicrogyria gene, ADGRG1, in two affected members." (PMID 34848785, 2021). "ADGRG1 is essential for the frontal cortex development in which function-deficient mutations lead to a severe malformation called bilateral frontoparietal polymicrogyria (BFPP)." (PMID 34367958, 2021). "For example, dysfunction of ADGRG1/GPR56 causes polymicrogyria, ADGRF5/GPR116 controls pulmonary surfactant production, genetic lesions in many aGPCR loci are associated with a roster of cancer types and ADGRE2/EMR2 regulates mast cell degranulation." (PMID 28784204, 2017). "For example, rs121908462 is a pathogenic variant associated with polymicrogyria that falls in ADGRG1, an adhesion G protein-coupled receptor G1." (PMID 27268795, 2016). "Examples are ADGRG1 (GPR56) and ADGRV1 (VLGR1), where gene mutations cause brain malformation (bilateral frontoparietal polymicrogyria) and a form of Usher syndrome, respectively." (PMID 27516204, 2016). "In addition to detecting pathogenic variants in genes previously linked to polymicrogyria (eg, ADGRG1/GPR56, SCN3A, TUBB2B), we discovered 6 genes linked to polymicrogyria for the first time (QRICH1, TMEM161B, PANX1, KIF26A, SCN2A, and MAN2C1)." (PMID 37486637, 2023).
leukemia (15 papers, 2015 to 2026). A malignant (clonal) hematologic disorder, involving hematopoietic stem cells and characterized by the presence of primitive or atypical myeloid or lymphoid cells in the bone marrow and the blood. "Upon co-culture 48 h with leukemia blasts, ADGRG1+CD8+ T cells exhibited increased IFN-γ secretion, significantly surpassing the levels observed in ADGRG1−CD8+ T cells, suggesting the tumor reactivity of ADGRG1+CD8+ T cells." (PMID 39243082, 2024). "Besides serving as a marker for functional human hematopoietic stem cells and leukemia stem cells, ADGRG1 also acts as a specific cell surface marker for cytotoxic lymphocytes." (PMID 39243082, 2024). "Notably, ADGRG1 has also been found to serve as a marker for leukemia stem cells." (PMID 39243082, 2024). "Many leukemia stem cell like genes of the LSC17 signature diminished after day 14 such as LAPTM4B, MMRN1, ADGRG1 or AKR1C3, but some were upregulated again by day 30, day 70 CD19- and/or day 70 CD19+." (PMID 41145673, 2026). "We observed that ADGRG1+CD8+ T cells secreted higher levels of IFN-γ in the absence of leukemia cells." (PMID 39243082, 2024).
glioma (14 papers, 2012 to 2024). A benign or malignant brain and spinal cord tumor that arises from glial cells (astrocytes, oligodendrocytes, ependymal cells). "The loss of ADGRG1's function promotes radioresistance of glioma-initiating cells." (PMID 29805753, 2018). "For example, increased expression levels of ADGRG1, ADGRE5, and ADGRF5 has been detected in a variety of human cancers such as glioma (ADGRG1), gastric, pancreatic, esophageal, prostate, colorectal carcinomas (ADGRE5), and breast cancer (ADGRF5)." (PMID 29468160, 2018).
colorectal cancer (12 papers, 2017 to 2025). A primary or metastatic malignant neoplasm that affects the colon or rectum. "The proliferation of colorectal cancer cells mediated by ADGRG1 may require progesterone binding." (PMID 39935605, 2025). "Both ADGRG1 and ADGRG6 are involved in the progression of colorectal cancer." (PMID 39935605, 2025).
acute myeloid leukemia (11 papers, 2018 to 2025). Acute myeloid leukemia (AML) is a group of neoplasms arising from precursor cells committed to the myeloid cell-line differentiation. "A transcriptomic analysis of 772 GPCRs in 148 acute myeloid leukemia (AML) samples, encompassing different subgroups, identified ADGRG6 as one of 19 down‐regulated GPCRs, with others including the closely related ADGRG1 and SMO." (PMID 33735533, 2021).
bilateral frontoparietal polymicrogyria (9 papers, 2012 to 2025). "Mutations in ADGRG1, also known as GPR56, are known to cause autosomal recessive bilateral frontoparietal polymicrogyria (BFPP; MIM 606854), which includes intellectual disability as a main clinical feature." (PMID 34848785, 2021).
colon cancer (9 papers, 2017 to 2025). "EBV might use G protein-coupled receptor (GPCR) signaling, like EDNRA and ADGRG1, which are common DEGs in colon cancer." (PMID 39228892, 2024). "Moreover, EBV might use G protein-coupled receptor (GPCR) signaling, like EDNRA and ADGRG1, which are common DEGs in colon cancer." (PMID 41440381, 2025).
diabetes (7 papers, 2008 to 2025). "One example is ADGRG1 which is the most abundant G protein-coupled receptor in human pancreatic islets and plays an important role in pancreatic β-cell function, but has not previously been reported to be a circulating biomarker of diabetes." (PMID 33279861, 2021). "In total there were 44 out of 973 (4.5%) proteins that contributed significantly to the prediction of diabetes (FDR-corrected p<0.05) in the random forest model, the most important being NOS3, HGF, PON3, IGSF3, and ADGRG1." (PMID 33279861, 2021).
epilepsy (6 papers, 2020 to 2024). A brain disorder characterized by episodes of abnormally increased neuronal discharge resulting in transient episodes of sensory or motor neurological dysfunction, or psychic dysfunction. "ADGRG1, LGI3 and NEFM are known to play roles in neural development and are associated with neurological diseases, such as epilepsy." (PMID 37185447, 2023).
depression (5 papers, 2020 to 2025). "Decreased ADGRG1/Adgrg1 levels in the prefrontal cortex are associated with depression in humans and depressive-like behavior in mice." (PMID 34944065, 2021). "Furthermore, ADGRG1 knockdown mice were associated with depression-like behavior, executive dysfunction, and poor response to neurological treatment (e.g., antidepressant)." (PMID 36658485, 2023). "Down-regulation of ADGRG1 mediates depression in humans or depression-like behaviors in mice." (PMID 39935605, 2025).
rheumatoid arthritis (4 papers, 2021 to 2025). A chronic, systemic autoimmune disorder characterized by inflammation in the synovial membranes and articular surfaces. "In the immune system, soluble ADGRG1, which is elevated in the serum of rheumatoid arthritis patients, can be used as a biomarker for rheumatoid arthritis." (PMID 39935605, 2025). "Moreover, ADGRG1 (GPR56), known to be highly expressed in Tph cells of patients with anti-citrullinated protein antibody–positive rheumatoid arthritis, was prominently expressed in cells from CD8TΔhPBMC mice." (PMID 41277554, 2025).
viral infection (4 papers, 2017 to 2025). "Both populations expressed ADGRG1, which encodes GPR56, a marker of effector memory CD4+ T cells in virus infections and autoimmune diseases." (PMID 40956619, 2025).
multiple sclerosis (3 papers, 2021 to 2024). A progressive autoimmune disorder affecting the central nervous system resulting in demyelination. "CXCR4 and PTGER4 were higher expressed in subcortical white matter compared to cortical grey matter microglia, and ADGRG1 was downregulated in microglia obtained from normal-appearing white and grey matter tissue of multiple sclerosis (MS) brains." (PMID 34054860, 2021). "Two other proteins, ADGRG1 and PTN, were significant across the groups (controls and multiple sclerosis subtypes) according to Kruskal–Wallis/ANOVA test (FDR = 0.008 and FDR = 0.046, respectively)." (PMID 38978729, 2024). "When comparing gene expression in pure microglia from normal-appearing, non-lesional tissue of deceased multiple sclerosis (MS) autopsy cases and tissue of non-pathological brains, we found downregulation of ADGRG1 in both, white and grey matter, while expression of other GPCR genes was not changed." (PMID 34054860, 2021).
COVID-19 (2 papers, 2022 to 2024). A disease caused by infection with severe acute respiratory syndrome coronavirus 2. "Fifteen proteins were significantly increased in the severe group in comparison to healthy controls, of which pleiotrophin (PTN), adhesion G protein-coupled receptor G1 (ADGRG1) and C-C motif chemokine ligand 19 (CCL19) were the top three proteins most elevated in patients with severe COVID-19." (PMID 39767799, 2024).
cervical cancer (1 paper, 2021). A primary or metastatic malignant neoplasm involving the cervix. "Overall, the results confirmed that ADGRG1 contributes to tumorigenesis and progression in cervical cancer." (PMID 34367958, 2021). "Among them, 84.5% (49 of 58) of cervical cancer specimens showed significant overexpression of ADGRG1 protein." (PMID 34367958, 2021). "We examined ADGRG1 expression levels in cervical cancer cell lines by western blotting, including Hela, Caski, Siha, C33A." (PMID 34367958, 2021). "We investigated the available dataset of ADGRG1 expression profile in human cervical cancer from GEPIA." (PMID 34367958, 2021). "The expressions of ADGRG1 in cervical cancer cell lines Siha and Hela were significantly higher than those in Caski and C33A at the protein level." (PMID 34367958, 2021). "Gene Expression Profiling Interactive Analysis (GEPIA) was searched to show the expression level of ADGRG1 in cervical cancer and normal tissue." (PMID 34367958, 2021). "We found the ADGRG1 was significantly overexpressed in cervical cancer tissues compared to corresponding normal tissues." (PMID 34367958, 2021). "Our study found that ADGRG1 was upregulated in cervical cancer tissues compared to the adjacent normal cervix." (PMID 34367958, 2021). "To summarize, knockdown of ADGRG1 decreases tumorigenesis via blockade of the P13K/Akt/mTOR axis in cervical cancer." (PMID 34367958, 2021). "Based on the expression profile from GEPIA, ADGRG1 was overexpressed in cervical carcinoma compared with normal cervix uteri." (PMID 34367958, 2021). "Nevertheless, the biological function of ADGRG1 remains poorly understood in cervical cancer." (PMID 34367958, 2021). "Correlations between ADGRG1 expression and clinicopathologic characteristics in cervical cancer." (PMID 34367958, 2021). "So, high expression of ADGRG1 predicts poor prognosis in cervical cancer." (PMID 34367958, 2021). "We found that ADGRG1 was overexpressed in cervical carcinoma compared to normal cervix uteri." (PMID 34367958, 2021). "Thus, ADGRG1 may represent a potential prognostic marker and possible therapeutic target for cervical cancer." (PMID 34367958, 2021). "However, the clinical significance and potential possible mechanism of ADGRG1 in regulating tumorigenesis of cervical cancer remain unclear." (PMID 34367958, 2021).
demyelination (1 paper, 2018). "Having found that the interaction of microglial TG2 with OPC-derived ADGRG1 sustained OPC proliferation during developmental myelination, we next asked if this interaction was relevant during myelin repair in the adult CNS using two established murine models of toxin-induced demyelination." (PMID 29809138, 2018).
fibrosis (1 paper, 2024). the formation of excess fibrous connective tissue in an organ or tissue in a reparative or reactive process. "For example, ADGRG1 and IGSF9, both upregulated in PLHIV with fibrosis, were positively correlated with T2DM, presence of carotid plaques, prior myocardial infarction, duration of HIV and ART, and prior exposure to D-drugs and INSTI." (PMID 39426127, 2024).
lymph node metastasis (1 paper, 2021). "As a result, the expression level of ADGRG1 was significantly associated with FIGO stage (P = 0.0455), lymph node metastasis (P = 0.0426), depth of interstitial infiltration (P = 0.0140)." (PMID 34367958, 2021).
secondary progressive multiple sclerosis (1 paper, 2024). A multiple sclerosis with a clinical course characterized by a progressive accumulation of neurological disability, independent of relapses, following an initial relapsing-remitting (RR) phase. "PTN and ADGRG1 were also significantly different between relapsing–remitting multiple sclerosis and secondary progressive multiple sclerosis (FDR = 0.0053 and FDR = 0.041, respectively)." (PMID 38978729, 2024).